EZH2 (enhancer of zeste 2 polycomb repressive complex 2 subunit)
Diseases named in the same sentence as EZH2 in open-access papers (continued):
Sharing a sentence is not in itself a finding about the gene and the disease.
tumor (continued). "AKT-mediated phosphorylation of EZH2 suppresses trimethylation of lysine 27 in histone H3, facilitating the transcription of target genes to suppress tumor growth." (PMID 35935878, 2022). "EZH2 overexpression in TNBC is known to enhance tumor progression and metastasis and is associated with advanced tumor stage and increased mortality." (PMID 35177654, 2022). "In this review, first we describe the most frequent epigenomic alterations in FL (KMT2D, CREBBP and EZH2) that affect the immunological niche, and their potential consequences on the informational transfer between tumor B cells and their microenvironment." (PMID 35022084, 2022). "EZH2 possesses a crucial role in chromosomal remodeling, as well as in the regulation of the silencing of several tumor suppressor genes and those involved in immune cell development." (PMID 36142846, 2022). "Tumor-suppressor pseudogene RRN3P3 upregulated the expression of EZH2 by competitively binding hsa-miR-26a-5p and hsa-miR-26b-5p, which explained the higher expression of EZH2 in the low-risk subtype." (PMID 36438489, 2022). "Multiple preclinical studies support that epigenetic modulators—and, notably, EZH2 inhibitors—have the potential to modulate tumor’s immunogenicity and anti-tumor immune response." (PMID 35327458, 2022). "Evidence has shown that the PARP inhibition effect is dependent on the infiltration degree of T cells; however, EZH2 downregulates the degree of T-cell infiltration in the tumor microenvironment, which hurdles the effect of PARP inhibitors." (PMID 36263120, 2022). "Aberrant expression of PcG proteins like BMI1, CBX8, and EZH2 is mainly responsible for the deposition and maintenance of pro-tumor histone modification in HCC." (PMID 36566204, 2022). "Although EZH2 works in a variety of ways, including the canonical pathway of epigenetic transcription and gene upregulation, it can also work as a tumor suppressor." (PMID 35955891, 2022). "Overexpression of Ezh2 significantly delayed DMG development that was reflected in the significantly decreased tumor incidence and reduced proliferation rate of these tumors." (PMID 35395831, 2022). "Our analysis revealed that EZH2 regulates the tumour immune microenvironment in LIHC, which is related to the activation and regulation of B-cell, DC, and T-cell immune responses." (PMID 35659256, 2022). "EZH2 KO prolongs the survival of DMG tumor bearing mice and proliferation can be impaired by a SUZ12 knockdown." (PMID 34762160, 2022). "As a tumor-promoting factor, AR signaling enhances EZH2 expression to inhibit apoptosis and provide enzalutamide resistance." (PMID 35236381, 2022). "It was reported that EZH2 regulates macrophage activation through the miR-29b/miR-30d-LOXL4 axis and enhances tumor-associated macrophage (TAM) infiltration in breast cancer." (PMID 36713412, 2022). "On the contrary, EZH2 depletion led to DNA demethylation and subsequent upregulation of miR-124-3p level, which inhibited its target CCL2 expression in the tumor cells, causing arrest of TAMs M2 polarization." (PMID 36038549, 2022). "EZH2 is involved in global transcriptional repression, which plays an important role in cancer progression by silencing tumor‐suppressor genes." (PMID 35604910, 2022). "We found that M2 marker genes were significantly highly expressed in EZH2 inhibitor-treated tumor tissues, while M1 markers didn’t show any consistent changes." (PMID 36038549, 2022). "Recent studies have shown that multiple tumour-related lncRNAs regulated cancer progression through interactions with enhancer of Zeste 2 Polycomb repressive complex 2 subunit (EZH2) and LSD1." (PMID 35327654, 2022). "In these cancers, even though EZH2 is overexpressed, tumor cells paradoxically fail to maintain a wild-type dose of H3K27me3." (PMID 35046519, 2022).
tumor (continued). "As the major H3K27me3 methyltransferase, EZH2 is commonly believed to execute its tumor-promoting function via transcriptional repression of tumor suppressor genes." (PMID 35013218, 2022). "Although slightly higher expression levels were observed in tumor samples, the expression levels of these transcripts were much lower than EZH2/JARID2 specifically bound genes in HepG2 cells." (PMID 36578923, 2022). "In the tumor model, EZH2 inhibition triggers antigen processing and promotes anti-tumor T cell infiltration, and potentiates anti-PD1 therapy." (PMID 35912007, 2022). "The B16 tumor cells were used to assess the lung metastasis, in the EZH2 knockdown cells, the lung metastasis were reduced significantly." (PMID 35912007, 2022). "In Kras-driven lung adenocarcinoma mouse model, loss of Ezh2 release the insulin-like growth factor 1 (Igf1), further amplify the activation of Akt-ERK signaling and promote tumor formation." (PMID 36263120, 2022). "It is worth noting that EWS-FLI1 binds to the EZH2 promoter to activate embryonic tumor stem cell growth and metastatic spread." (PMID 35454895, 2022). "Tumor-associated endothelial cells, in response to VEGF, overexpress EZH2 which stimulates tumor angiogenesis by the inhibition of vasohibin-1." (PMID 35269636, 2022). "As the expression of EZH2 was found to be increased in HNSCC, and the silencing of EZH2 led to the suppression of tumour invasion, this protein seems to be a promising target for therapies; however its association with PNI has to be evaluated yet." (PMID 35571032, 2022). "Just poorly differentiated tumor tissues show elevated activity of enhancer of zeste homolog 2 (EZH2), a histone-lysine N-methyltransferase enzyme, that is involved in histone methylation and consecutively, in transcriptional repression." (PMID 35814409, 2022). "Similar to the wild-type EZH2 re-expressing 231.KO#1.EZH2 cells, 231.KO#1.H689A cells that re-expressing EZH2 methyltransferase-dead mutant H689A had enhanced tumor cell proliferation and osteoclast maturation compared to 231.KO#1.pLenti cells." (PMID 35538070, 2022). "Silencing EZH2 has been found to effectively inhibit malignant behaviors of tumor cells, which has hence spurred tremendous efforts to find novel and efficient EZH2 inhibitors." (PMID 36071871, 2022). "Our results demonstrated that targeting EZH2 therapy reprograms the tumor immunogenicity by inducing a significant increase in CD4+ and CD8+ T cells within the tumor microenvironment." (PMID 35912007, 2022). "The results showed that TNBC patients under 60 years old who carried a TC or CC genotype at EZH2 rs6950683 and re3757441 had a tumor size of 20 mm or smaller (T1)." (PMID 35813302, 2022). "We confirmed that EZH2 converts TAMs to a tumor-promoting M2 phenotype to facilitate BC progression and metastasis." (PMID 36038549, 2022). "On the other hand, when EZH2 was specifically silenced in the tumor cells there was a dramatic drop in lymph metastasis which suggests a pro-migration function of EZH2 overexpression." (PMID 36359771, 2022). "LINC00152 can also promote the growth of tumor cells, both in vivo and in vitro, by binding enhancer of zeste homolog 2 (EZH2) and regulating the CXC motif chemokine ligand 9 (CXCL9) and CXCL10/CXCR3 axes in CD8T cells." (PMID 36033524, 2022). "The histone methylator EZH2 can also be targeted to remove repression of silenced genes, including tumor suppressors." (PMID 35954407, 2022). "Inhibition of EZH2 and BET proteins by specific inhibitors have also been reported to repress CSC-associated tumor aggressiveness in different solid cancers." (PMID 35438143, 2022). "DAB2IP, also known as a tumor suppressor in ccRCC, has been reported to be epigenetically repressed by EZH2-mediated methylation of lysine 27 in histone H3 (H3K27me3), and also be degraded by SMURF1-mediated ubiquitin-proteasome regulation." (PMID 35562342, 2022).
tumor (continued). "In pre-clinical models, the inhibition of DNMT1 and EZH2 improves the efficacy of immune checkpoint inhibitor therapy, slows tumour progression and increases TH1-cytokine production." (PMID 35326684, 2022). "The combination of FXR agonist plus EZH2 inhibitor exerts synergistic tumor inhibition in CRC both in vitro and in vivo by dramatically accelerating FXR nuclear location and cooperatively upregulating CDX2 expression." (PMID 35449124, 2022). "Methylation at Lys735 (K735) and Phosphorylation at Thr261 (T261) increased the protein stability and catalytic activity of EZH2, further attenuating its transcriptional repression on tumor suppressors." (PMID 36076977, 2022). "Subsequently, we explored the relationship between EZH2 expression and immune infiltration in 39 tumour types by using the TIMER database (Figure." (PMID 35659256, 2022). "Beyond the traditional oncogenic role, EZH2 also acts as a tumor-suppressor in certain condition, which possibly brings limitation to the combined strategy." (PMID 36263120, 2022). "EZH2i lead to deprivation of the enzymatic activity of EZH2, which for example contributes to low H3K27me3 levels and subsequent anti-tumor effects." (PMID 36497404, 2022). "EZH2 is a key tumour‐targeting molecule and DZNep is an effective histone methyltransferase inhibitor." (PMID 35257481, 2022). "EZH2 expression was significantly greater in the tumor and polyp tissues in comparison to adjacent normal tissues." (PMID 34923811, 2022). "It is noteworthy that the most the circRNAs investigated to date are tumor-promoting factors and their mechanism of action is suggested by sponging miRNAs to enhance EZH2 expression." (PMID 35236381, 2022). "Enhanced EZH2 activity is reported to induce tumor growth and resistance to conventional chemotherapy, leading to poor prognostic outcomes." (PMID 35438143, 2022). "For the specifically EZH2-bound genes in the THLE-2 cell line, although their difference between tumor and normal was significant (p-value = 0.02, K–S test), the expression level was much lower than the all-expressed and HepG2-specific EZH2-bound genes." (PMID 36578923, 2022). "The combination of this EZH2 inhibitor and anti-PD-1 treatment showed an enhanced anti-tumor effect in syngeneic mouse models." (PMID 35163049, 2022). "The mutant H3 K27M binds to EZH2, which interferes with the methyltransferase activity resulting in hypermethylation and increased tumor formation." (PMID 35629262, 2022). "MAGI2-AS3 downregulates HOXB7 via histone methyletransferase EZH2 to initiate H3K27me3, which is required for the EZH2-mediated repression of various genes that are vital for carcinogenesis and tumor development." (PMID 36294743, 2022). "For instance, EZH2, a histone 3 lysine 27 trimethylation regulator, mediates epigenetic silencing of tumor CXCL9 and CXCL10, two Th1-type chemokines, and consequently represses effector T cell trafficking into the tumor microenvironment." (PMID 35664070, 2022). "Our findings indicate that ERβ+ tumors exhibit different characteristics compared to ERβ− tumors and demonstrate that ERβ functions as a molecular switch for EZH2, repurposing it for tumor suppressive activities and repression of oncogenic p65 signaling." (PMID 35177654, 2022). "STAT3 and EZH2 are potential molecular biomarkers for tumor progression and serve as poor predictors of outcomes." (PMID 35208478, 2022). "Specifically, recent studies have shown that EZH2 inhibition can increase tumor expression of the disialoganglioside GD2 and enhance efficacy of anti-GD2 therapies." (PMID 36589742, 2022). "Given the importance of EZH2 to late-stage metastatic ovarian cancer, EZH2 inhibition would appear to be a viable target for drug treatment; however, few small molecule studies have been undertaken in this tumor type." (PMID 36359771, 2022). "The results showed that G9a and EZH2 were expressed at markedly higher levels in primary tumor samples than in normal tissue samples." (PMID 35409271, 2022).
tumor (continued). "In particular, it serves as a tumor suppressor in diverse malignancies by targeting critical oncogenes or anti-oncogenes, including EZH2, DNMT3a, MALAT-1, ZEB1, and USP47." (PMID 35205710, 2022). "But in tumor models, EZH2 inhibits the expression of pro-inflammatory genes and pathways, such as SOCS3, STAT1, STAT3, etc.." (PMID 35432300, 2022). "Overall, our observations suggest a tumor suppressive role of Ezh2 in DMG, even though there are isolated clinical cases of DMG which have reported a similar gain-of-function Ezh2 mutation." (PMID 35395831, 2022). "Further, the serial bioluminescence imaging and analysis of harvested organs from control EZH2 KD tumor-bearing mice reveal that the depletion of EZH2 restricts the peritoneal metastasis as compared to the respective control." (PMID 36446780, 2022). "A detailed transcriptomic study of prostate cancer PDX models outlines the important role of the polycomb-repressive complex 2 (PRC2) and EZH2, of the G2-M checkpoints and of macrophage polarization in tumor progression." (PMID 35682963, 2022). "A previous study demonstrated a precision treatment strategy for EZH2-aberrant tumors that was based on tumor-intrinsic MLL1 expression and concurrent inhibition of epigenetic crosstalk and feedback MAPK activation." (PMID 36127339, 2022). "To explore the role of EZH2 inhibition in regulating antigen presentation of tumor cells in vivo, we analyzed the tumor samples after tumor implantation for 12 days." (PMID 35912007, 2022). "Several other recent studies have revealed the role of Ku 70/80 and EZH2 in regulating NHEJ activity in tumor cells." (PMID 36091750, 2022). "With respect to the tumor-promoting role of EZH2, its inhibition should significantly diminish the survival of cancer cells." (PMID 35236381, 2022). "Remarkably, EC patients had higher levels of known oncogenes (including STAT3 and EZH2) and lower levels of the known tumor suppressor lncRNA MEG3 when compared to normal samples." (PMID 35712514, 2022). "The decreased Ki67 index in EZH2 and PTEN-depleted uteri versus that in PTEN-depleted uteri indicated an oncogenic role of EZH2 during early tumor development." (PMID 35269532, 2022). "This study showed that anti-CTLA-4 therapies lead to the upregulation of EZH2; therefore, the combination of EZH2 inhibition with ipilimumab enhances efficacy in tumor-bearing mice, providing a rationale for combining both therapies." (PMID 36135315, 2022). "BMAL1 inhibits tumor progression by suppressing glycerolipid metabolism through transcriptional inhibition of GPAM expressions in an EZH2 dependent way." (PMID 36439870, 2022). "A EZH2 selective inhibitor reduces the cytotoxic activity of phagocytosis and induces PD-1 overexpression in macrophages, leading to the development of tumor growth." (PMID 35163049, 2022). "The imbalance of this negative feedback pathway continuously increases the expression level of EZH2, thus promoting the proliferation of tumor cells." (PMID 36497343, 2022). "Due to the selectivity of PRC2-mediated gene silencing, EZH2 functions oncogenic or tumor-suppressive role in human malignancies." (PMID 35449124, 2022). "Addition of MG132 consistently rescued the MYCN loss caused by EZH2 depletion in NCI-H526 cells, arguing that EZH2 regulates MYCN stabilization in these tumor cells." (PMID 35013218, 2022).
tumor (continued). "Here, we will focus on the mutations of the histone acetyltransferase CREBBP and the methyltransferases KMT2D and EZH2 that play a key role in the FL microenvironment, and have detrimental consequences on the anti-tumor immune response." (PMID 35022084, 2022). "The work presented in the current study provides an analysis of the role of EZH2 levels in LIHC and explores the function of EZH2 in tumour immunity, which was derived from publicly accessible databases." (PMID 35659256, 2022). "PRC2-independent functions of EZH2 have been described in many other tumor entities by different authors." (PMID 35740494, 2022). "The immunohistochemistry of EZH2 showed that EZH2 is mainly located in the nuclear and highly expressed in tumor tissues compared with normal tissues." (PMID 36038907, 2022). "EZH2 (a histone methyltransferase) has been shown to promote immune escape by inhibiting MHC-I-mediated antigen presentation in a variety of tumours." (PMID 36276947, 2022). "Here, we further explored the anti‐tumour effects of MEG3 in vivo and attempted to clarify the specific molecular mechanisms underlying the regulatory loop of MEG3 and EZH2." (PMID 35257481, 2022). "Next, we wanted to distinguish the role of EZH2 on tumor cell autonomous effect versus adaptive anti-tumor immunity." (PMID 35912007, 2022). "In EC, EZH2 expression is increased in tumor samples compared to normal tissue, and high EZH2 expression correlates with decreased progression-free survival or overall survival." (PMID 35326450, 2022). "Logistic regression analysis showed that high expression of RUNX3, low expression of EZH2, and clinical N (cN) stage were good predictors of tumor regression response and down-staging." (PMID 35280723, 2022). "Multivariate analysis using the Cox proportional hazard model was performed and included stratification factors such as tumour grade, tumour focality, adjuvant therapy status, and EZH2 immunoexpression." (PMID 36292072, 2022). "Studies have shown that EZH2 (which contributes to tumor proliferation), and CDK6, a critical regulator of cell cycle transition in G1/S, are both upregulated in GBM and are direct target genes of miRNA-13834." (PMID 35835978, 2022). "While the percentage of CD31+ area in EZH2 knockdown tumor tissues was much lower than that in control tumors due to a reduced secretion of VEGF by TAMs." (PMID 36038549, 2022). "EZH2 is a vital mediator of gene expression by H3K27me3 that emerges as a novel agent in tumor treatment." (PMID 35414117, 2022). "High levels of EZH2 were observed in the tumor section derived from RKO/Par4a clone inoculation, while there was nearly none in the tissue sections obtained following inoculation with the RKO parental cells." (PMID 35955891, 2022). "Our Ezh2 gain-of-function model, on the other hand, reduced tumor incidence and significantly improved survival along with a positive enrichment of the oxidative phosphorylation pathway." (PMID 35395831, 2022). "Meanwhile, EZH2 showed a positive correlation with biomarkers of immune cells and the chemotactic activity of tumor-related immune cells." (PMID 35627262, 2022). "We demonstrate that EZH2 is nearly exclusively expressed in highly proliferative neoplasms and is a robust biomarker for identifying aggressive G3 tumors with poor prognosis." (PMID 35740494, 2022). "190,191 Pharmacological EZH2 inhibition induces a change in the production of pro-inflammatory cytokines which promotes anti-tumor activity and significantly increases the ratio between CD8+ T and Tregs in the tumor microenvironment." (PMID 35046519, 2022). "Of note, both tumor-promoting and tumor-suppressive effects of EZH2 have been documented in cancer development." (PMID 35269532, 2022). "Repression of EZH2 in tumor-infiltrating Treg cells thus promote pro-inflammatory signaling and enhance recruitment of CD8+ and CD4+ effector T cells, ultimately leading to tumor regression." (PMID 35438143, 2022).